CHST4 (carbohydrate sulfotransferase 4)
Description:
Sulfotransferase involved in SELL/L-selectin ligand biosynthesis pathway. Catalyzes the transfer of the sulfate group from 3'-phospho-5'-adenylyl sulfate (PAPS) onto the hydroxyl group at C-6 position of the non-reducing N-acetylglucosamine (GlcNAc) residue within O-linked mucin-type glycans. Contributes to generate sialyl 6-sulfo Lewis X determinant (also known as MECA-79 epitope) for SELL recognition, a prerequisite for continuous lymphocyte homing into peripheral lymph nodes and antigen immune surveillance. Transfers the sulfate group primarily on core 2 GlcNAcbeta1-6(Galbeta1-3)GalNAcalphaSer/Thr and extended core 1 GlcNAcbeta1-3Galbeta1-3GalNAcalphaSer/Thr based O-linked glycans on CD34 and GLYCAM1 peripheral node addressins (PNAds) expressed on the lumenal side of high endothelial venules (HEVs). The recognition of PNAds by SELL initiates a multistep process comprising tethering and rolling of blood lymphocytes on HEVs against the blood flow, followed by chemokine signaling, integrin-mediated lymphocyte adhesion onto endothelial cells and lymphocyte transendothelial migration. Modulates rolling velocity and differential T and B lymphocyte recruitment into peripheral lymph nodes, with a major role in B lymphocyte homing. Might be redundant in sulfation of MADCAM1 and lymphocyte trafficking to mesenteric lymph nodes (By similarity). Can also sulfonate core 3 GlcNAcbeta1-3GalNAc-R based glycans as well as GlcNAcbeta1-3Galbeta1-Glc, GlcNAcbeta1-6ManOMe and GlcNAcbeta1-2Man oligosaccharides, which might be ectopically expressed during tumorigenesis.
Synonyms: LSST; HEC-GLCNAC-6-ST; GST3; GlcNAc6ST2; HECGLCNAC6ST
Tractability: Antibody: UniProt predicts a signal peptide or a membrane-spanning region. PROTAC: ubiquitination databases record sites on it.
Target class: Enzyme; Transferase
Gene: Protein-coding gene on chromosome 16 (71,525,233 to 71,541,950, forward strand). Ensembl gene ENSG00000140835.
Subcellular location: Golgi apparatus membrane
Pathways (Reactome):
Metabolism of proteins: O-linked glycosylation of mucins
Gene Ontology:
Molecular function: N-acetylglucosamine 6-O-sulfotransferase activity; sulfotransferase activity
Biological process: N-acetylglucosamine metabolic process; sulfur compound metabolic process; cell adhesion; cell-cell signaling; immune response; positive regulation of leukocyte tethering or rolling; protein O-linked glycosylation via N-acetyl-galactosamine; protein sulfation; carbohydrate metabolic process
Cellular component: trans-Golgi network; Golgi membrane
Genetic constraint (gnomAD): Loss-of-function variants: 0 observed, 0.49 expected, observed/expected ratio (o/e) 0, 90% interval 0 to 1.84. That is too few expected variants to judge how well the gene tolerates losing a copy. Missense variants: 466 observed, 518.92 expected, observed/expected ratio (o/e) 0.9, 90% interval 0.83 to 0.97. Synonymous variants: 171 observed, 199.09 expected, observed/expected ratio (o/e) 0.86, 90% interval 0.76 to 0.98.
Homologues: Orthologues: chimpanzee CHST4 (99% identical), macaque CHST4 (96% identical), dog CHST4 (80% identical), pig CHST4 (80% identical), rabbit CHST4 (78% identical), guinea pig CHST4 (73% identical), mouse Chst4 (73% identical), rat Chst4 (72% identical), tropical clawed frog chst5 (51% identical), Drosophila melanogaster CG31637 (21% identical), Drosophila melanogaster CG9550 (16% identical). Paralogues in human: CHST6 (54% identical), CHST5 (51% identical), CHST2 (34% identical), CHST7 (34% identical), CHST1 (31% identical), CHST3 (30% identical).
Diseases named in the same sentence as CHST4 in open-access papers:
CHST4 is named in the same sentence as 45 diseases in open-access papers, as found by Europe PMC text mining. Sharing a sentence is not in itself a finding about the gene and the disease. The quoted sentences say what the papers report.
hepatocellular carcinoma (3 papers, 2020 to 2024). A malignant tumor that arises from hepatocytes. "Many reports have revealed the function of CHST4 in malignant tumors, most frequently in hepatocellular carcinoma, suggesting that genetic background has a role in the response rate after immunotherapy." (PMID 38396947, 2024). "In particular, we found that CHST4 expression was downregulated in hepatitis B virus-related hepatocellular carcinoma (HBV-HCC) tumors compared to paired normal tissue." (PMID 33178582, 2020). "Previous reports have already indicated that CHST4 was preferentially expressed in HCC, and it may function as a wonderful diagnosis signal for hepatocellular carcinoma (HCC) patient survival, with higher expression predicting shorter time-to-relapse (TTR) and overall survival (OS)." (PMID 35294478, 2022).
mesothelioma (3 papers, 2020 to 2025). A usually malignant and aggressive neoplasm of the mesothelium which is often associated with exposure to asbestos. "Through an extensive survival analysis of the TCGA mesothelioma dataset, the carbohydrate sulfotransferase 4 (CHST4) gene emerged as a promising indicator of favorable OS in patients with mesothelioma." (PMID 40362535, 2025). "Notably, CHST4 mRNA expression in mesothelioma demonstrated a significant correlation with immune–gene signatures representing tumor-infiltrating lymphocytes." (PMID 40362535, 2025). "Emerging molecular targets in mesothelioma include mesothelin (MSLN), oxytocin receptor (OXTR), protein arginine methyltransferase (PRMT5), and carbohydrate sulfotransferase 4 (CHST4)." (PMID 40362535, 2025). "CHST4 was highly expressed in cholangiocarcinoma (CHOL), mesothelioma (MESO), and prostate adenocarcinoma (PRAD), and was only lowly expressed in skin cutaneous melanoma (SKCM) and uveal melanoma (UVM)." (PMID 33178582, 2020).
cholangiocarcinoma (2 papers, 2020 to 2022). A carcinoma that arises from the intrahepatic biliary tree (intrahepatic cholangiocarcinoma) or from the junction, or adjacent to the junction, of the right and left hepatic ducts (hilar cholangiocarcinoma). "The change rate of CHST4 (primarily gene amplification) was highest in cholangiocarcinoma, followed by melanoma and uterine cancer (mainly gene mutation)." (PMID 33178582, 2020). "Consistent with previous studies, we found that the expression of CHST4 mRNA was higher in cholangiocarcinoma, colon adenocarcinoma, and gastric adenocarcinoma, and we partially verified this conclusion immunohistochemically." (PMID 33178582, 2020).
colitis (2 papers, 2023 to 2024). Inflammation of the colon. "Through cohousing experiments, we demonstrated that the weight gain and increased colitis susceptibility observed in Chst4–/– mice were highly dependent on microbiota alterations." (PMID 37463055, 2023). "Chst4–/– mice, which lack GlcNAc-6-O-sulfation of mucin O-glycans, developed obesity and were susceptible to experimental colitis as well as colitis-associated cancer (CAC)." (PMID 37463055, 2023). "Chst4–/– mice develop low-grade intestinal inflammation and increased susceptibility to DDS-induced colitis." (PMID 37463055, 2023). "Moreover, Parabacteroides goldsteinii, which has been reported to suppress both obesity and colitis, was increased in cohoused Chst4–/– mice." (PMID 37463055, 2023). "Since we observed low-grade intestinal inflammation in Chst4–/– mice, we hypothesized that Chst4–/– mice might be more sensitive to chemically induced colitis." (PMID 37463055, 2023).
colonic mucinous adenocarcinoma (2 papers, 2021 to 2022). "CHST4 is also up-regulated in paediatric precursor-B acute lymphoblastic leukaemia and colonic mucinous adenocarcinoma." (PMID 33741523, 2021). "It was detected that CHST4 has a highly expression in mucinous adenocarcinomas, in which core 1- and core 2-based-glycans were prolong by CHST4 through adding sulfate, but not in the nonmalignant tissues." (PMID 35294478, 2022).
intrahepatic cholangiocarcinoma (2 papers, 2020 to 2022). A carcinoma that arises from the intrahepatic bile duct epithelium in any site of the intrahepatic biliary tree. "CHST4 expression is also elevated in gastric cancer tissues, urothelial bladder carcinoma, cholangiolocellular carcinoma, and Opisthorchis viverrini (OV)-related intrahepatic cholangiocarcinoma, and the CHST4 promoter is hypermethylated in HBV-HCC." (PMID 33178582, 2020).
ovarian carcinoma (2 papers, 2020 to 2022). A malignant neoplasm originating from the surface ovarian epithelium. "Similarly, differences in CHST4 expression were previously observed among the various subtypes of colon adenocarcinoma and ovarian cancer." (PMID 33178582, 2020). "In the serum of uterine cervical and corpus cancer, CHST4 provided respectively higher positive rates than cancer antigen 125 (CA125), while it provided lower positive rates for ovarian cancer than CA125." (PMID 35294478, 2022).
adenoma (1 paper, 2023). A neoplasm arising from the epithelium. "Histological analysis revealed lower-grade adenomas in WT mice relative to Chst4–/– mice." (PMID 37463055, 2023).
bladder urothelial carcinoma (1 paper, 2020). "Finally, in bladder urothelial carcinoma (BLCA) and glioblastoma multiforme (GBM), those with high CHST4 expression had shorter DFS than those with low expression." (PMID 33178582, 2020).
breast carcinoma (1 paper, 2023). "In the present study, we have revealed that the expression of CHST2 is induced by Snail in breast cancer cells, while CHST4 expression is not affected by Snail." (PMID 37095090, 2023).
breast invasive carcinoma (1 paper, 2020). "Among the subtypes of breast invasive carcinoma (BRCA), the CHST4 expression in BRCA-basal was significantly higher than in BRCA-Her2 and BRCA-luminal." (PMID 33178582, 2020).
Cirrhosis (1 paper, 2020). A chronic disorder of the liver in which liver tissue becomes scarred and is partially replaced by regenerative nodules and fibrotic tissue resulting in loss of liver function. "Moreover, when we combined CHST4 with three other independent prognostic factors (multinodular, cirrhosis, and BCLC stage), the predictive value for prognosis significantly improved." (PMID 33178582, 2020). "We also showed that CHST4 is a prognostic candidate for HBV-HCC, particularly if its expression is combined with multinodular, cirrhosis, and BCLC stage." (PMID 33178582, 2020).
colon adenocarcinoma (1 paper, 2020). "Five types of human tumors showed higher mRNA expression of CHST4 in the tumor compared to the adjacent normal tissue, including colon adenocarcinoma (COAD), stomach adenocarcinoma (STAD), and kidney renal papillary cell carcinoma (KIRP)." (PMID 33178582, 2020).
colon cancer (1 paper, 2024). "DDX58, XAF1, OAS1, IFI27, IFI44 or IFIT3 was indeed downregulated and CHST4 or TNFSF18 was upregulated in MDM4 overexpressed colon cancer cells." (PMID 38281029, 2024). "We selected eight representative immune-related molecules for qPCR validation in SW480 and another colon cancer cell line HT29: DDX58, CHST4, TNFSF18, XAF1, OAS1, IFI27, IFI44, IFIT3." (PMID 38281029, 2024).
colorectal adenocarcinoma (1 paper, 2020). The most common type of colorectal carcinoma. "Moreover, CHST4 was moderately expressed in colorectal adenocarcinoma but not expressed in paired normal tissues." (PMID 33178582, 2020).
duodenal adenocarcinoma (1 paper, 2020). A carcinoma that arises from glandular epithelial cells of the duodenum. "The CHST4 was weakly expressed in cervical squamous carcinoma, gastric adenocarcinoma, thyroid papillary carcinoma, renal clear cell carcinoma, and duodenal adenocarcinoma compared to the matched normal tissues." (PMID 33178582, 2020).
gastric adenocarcinoma (1 paper, 2020). "CHST4 was distributed in the nuclei in LIHC and gastric adenocarcinoma; in all other tissues, it was distributed in the cytoplasm." (PMID 33178582, 2020).
glioma (1 paper, 2022). A benign or malignant brain and spinal cord tumor that arises from glial cells (astrocytes, oligodendrocytes, ependymal cells). "The altered the expression degree of CHST4 was discovered from glioma, where its mutation and amplifications are correlated with poor prognosis." (PMID 35294478, 2022).
head and neck squamous cell carcinoma (1 paper, 2020). A squamous cell carcinoma that arises from any of the following anatomic sites: lip and oral cavity, nasal cavity, paranasal sinuses, pharynx, larynx, and salivary glands. "In head and neck squamous cell carcinoma (HNSCC), CHST4 expression was higher in human papillomavirus (HPV)-positive subtypes than those that were HPV-negative." (PMID 33178582, 2020).
liver cancer (1 paper, 2023). An epithelial or non-epithelial malignant neoplasm that arises from the liver. "PILC-BSCSO identifies a subset of five marker genes, including prognostic biomarkers HMMR, CHST4, and COL15A1, that have excellent predictive potential for liver cancer using TCGA data." (PMID 37892853, 2023).
liver fibrosis (1 paper, 2022). "In line with the fundamental role of HSCs in producing extracellular matrix components and the initiation, progression, and regression of liver fibrosis, we found carbohydrate sulfotransferase 4 (CHST4) among their top 10 specific proteins." (PMID 35579278, 2022).
lymphoma (1 paper, 2020). A malignant (clonal) proliferation of B- lymphocytes or T- lymphocytes which involves the lymph nodes, bone marrow and/or extranodal sites. "Both mRNA expression and copy number of CHST4 were highest in the pancreas, colon, lung non-small-cell, and lymphoma Burkitt cell lines." (PMID 33178582, 2020).
metabolic syndrome (1 paper, 2023). A cluster of metabolic risk factors for CARDIOVASCULAR DISEASES and TYPE 2 DIABETES MELLITUS. "Transfer of bacteria from Chst4–/– mice resulted in significant weight gain and symptoms of metabolic syndrome, compared with bacteria transferred from WT mice." (PMID 37463055, 2023). "Consistently, the greater adipose mass and symptoms of metabolic syndrome, including lipid accumulation, fatty liver, and aberrant adipocyte size, in Chst4–/– mice were completely prevented by cohousing with WT mice." (PMID 37463055, 2023). "Considering greater weight gain and symptoms of metabolic syndrome in Chst4–/– mice, we sought to determine whether microbiota was essential for the observed weight gain." (PMID 37463055, 2023).
Obesity (1 paper, 2023). Accumulation of substantial excess body fat. "The genus Romboutsia, which is increased in patients with obesity and associated with body weight gain, was also increased in the ileal microbiota of Chst4–/– mice." (PMID 37463055, 2023). "Furthermore, our findings indicate that the susceptibility of Chst4–/– mice to HFD-induced obesity reemerged after they were separated following the cohousing period." (PMID 37463055, 2023). "Next, we investigated whether Chst4–/– mice regain the susceptibility to HFD-induced obesity when they were separated again after cohousing." (PMID 37463055, 2023). "Prompted by these findings and the significant role of intestinal microbiota in the development of obesity and intestinal inflammation, we investigated via 16S V3-V4 rRNA sequencing whether Chst4 deficiency alters the intestinal microbiota in 7-week-old mice fed with normal chow." (PMID 37463055, 2023). "From our experiments, it is clear that the bacteria in Chst4–/– mice are the driving force for obesity and intestinal inflammation." (PMID 37463055, 2023). "Importantly, we observed an increased abundance of Firmicutes and less Bacteroidota, a microbiota feature of obesity, at the phylum level in the ileal microbiota of Chst4–/– mice." (PMID 37463055, 2023). "We detected an increased IgA production in feces from WT compared with Chst4–/– mice, which could positively regulate gut microbiota to protect against obesity and intestinal inflammation." (PMID 37463055, 2023). "Furthermore, relative abundance of Prevotellaceae, which is increased in individuals with obesity and IBD, was increased in feces of Chst4–/– mice." (PMID 37463055, 2023).
thymoma (1 paper, 2022). A neoplasm arising from the epithelial cells of the thymus. "The results of Pearson correlation analysis showed that only LINC00452 was significantly and positively correlated with CHST4 (r = 0.49, p = 8.953 × 10−3) in the thymoma of patients with TAMG." (PMID 35432149, 2022). "We then confirmed that CHST4 and LINC00452, miR-204-3p and miR-204-5p were differentially expressed between patients with TAMG and thymoma patients without MG (NMG) by qPCR." (PMID 35432149, 2022).
triple-negative breast carcinoma (1 paper, 2024). An invasive breast carcinoma which is negative for expression of estrogen receptor (ER), progesterone receptor (PR), and human epidermal growth factor receptor 2 (HER2). "In the case of triple-negative breast cancer, CHST4 expression has also been identified as a prognostic factor when effective treatment options are limited." (PMID 38396947, 2024).
uterine corpus endometrial carcinoma (1 paper, 2020). A endometrial carcinoma (disease) that involves the body of uterus. "Additionally, in uterine corpus endometrial carcinoma (UCEC), those with high CHST4 expression had longer DFS than those with low expression." (PMID 33178582, 2020).
cancer (8 papers, 2020 to 2025). A tumor composed of atypical neoplastic, often pleomorphic cells that invade other tissues. "The other four genes, COCH, CST9, SOX11, and TDGF1, as well as CHST4, have also been implicated in the immune-related GO term, indicating the importance of immunomodulatory mechanisms in cancer therapy." (PMID 38396947, 2024). "Collectively, it suggests that CHST4 is an enzyme associated with different tumors, which also means it can be used as a biomarker for a variety of cancers." (PMID 35294478, 2022). "In accordance with this hypothesis, CHST4 was up-regulated in cancer tissues and associated with survival of patients with CoCC." (PMID 33741523, 2021). "Additionally, CHST4 is considered to be associated with tumor immunity against malignant tumors." (PMID 38396947, 2024). "The relationship between glycosyltransferase B3GNT3 and carbohydrate sulfotransferase CHST4 in HF remains unreported; however, both enzymes exhibit upregulated expression in cancers." (PMID 41268541, 2025). "Various solid tumors, such as mucinous adenocarcinoma, cervical cancer, and uterine cancer, show high levels of CHST4, suggesting its usefulness as a biomarker in malignant tumors." (PMID 38396947, 2024). "In this study, The Cancer Genome Atlas was used to perform a comprehensive survival analysis, which identified the CHST4 gene as a potential predictor of favorable overall survival for patients with MPM." (PMID 38396947, 2024). "It is assumed that CHST4 is involved in tumor immunity against malignant tumors, and functional analysis of CHST4 is expected to contribute to the development of immunotherapy." (PMID 38396947, 2024). "We used the Cancer Cell Line Encyclopedia (CCLE) database to explore the role of CHST4 in human tumor cell lines." (PMID 33178582, 2020). "Overall, the current evidence suggests that CHST4 is a cancer-related enzyme and is a potential biomarker in some tumor subtypes." (PMID 33178582, 2020). "Our study provides evidence that CHST4 expression may relate to tumor heterogeneity in several types of cancers." (PMID 33178582, 2020). "Carbohydrate sulfotransferase 4 (CHST4) plays an important role in lymphocyte homing and is abnormally expressed in several cancer types; however, its precise function in tumor development and progression is unknown." (PMID 33178582, 2020). "Therefore, this study aimed to clarify the function and clinical value of CHST4 in cancer by performing expression profiling in mice and human tumors." (PMID 33178582, 2020). "CHST4 localizes to HEVs in lymph nodes and, as a sulfotransferase, is involved in the generation of the MECA-79 epitope induced in chronic inflammatory tissues and malignant tumors." (PMID 38396947, 2024). "There was also a higher expression of CHST4 in metastatic in SKCM compared to non-metastatic cancer, and the expression of CHST4 was higher in the HPV-positive subtype of HNSCC than in the HPV-negative one." (PMID 33178582, 2020).